ERBB2 (erb-b2 receptor tyrosine kinase 2)
Diseases named in the same sentence as ERBB2 in open-access papers (continued):
Sharing a sentence is not in itself a finding about the gene and the disease.
breast cancer (continued). "The impact of PGC-1α and ERRα on glutamine enzyme expression was assessed in ERBB2+ breast cancer cell lines with quantitative RT-PCR, chromatin immunoprecipitation, and immunoblotting experiments." (PMID 24304688, 2013). "We found also a reduced expression of miR-125b in breast cancers strongly positive for ERBB2, that is coherent with its being a target of the miRNA." (PMID 24165569, 2013). "Our in vivo evidence for ErbB2+ tumors arising from Wnt signaling-inactive mammary epithelial cells is consistent with our previous reports and others on the potential cell origin of ErbB2-initiated mammary tumors." (PMID 24265712, 2013). "Here we demonstrate that ErbB2 overexpressing BT474 human breast cancer cells carry fully functional endogenous μ-opioid receptors." (PMID 23308242, 2013). "In the present work, we characterised the cat ERBB2 gene in normal samples and cat mammary lesion samples by different approaches in order to obtain novel information concerning the ERBB2 gene in the cat mammary tumour system (genome and proteome)." (PMID 24386251, 2013). "We and others have reported that after transgenic or virus-mediated activation of ErbB2 in the general mammary epithelium, mammary tumors rapidly develop." (PMID 24265712, 2013). "To do so, we used the ERRα pharmacological inhibitor C29 in the ERBB2+ human breast cancer cell lines SK-BR-3 and BT-474." (PMID 24304688, 2013). "It has been shown that erbB3 serves as a critical co-receptor of erbB2, and its expression is a rate-limiting factor for erbB2-induced breast cancer cell survival and proliferation." (PMID 24215614, 2013). "In this paper, we reveal that the PGC-1α/ERRα axis is a central regulator of glutamine metabolism in ERBB2+ breast cancer." (PMID 24304688, 2013). "In contrast, co-expression of erbB2 and erbB3 frequently occurs in breast cancers and breast cancer cell lines." (PMID 24168763, 2013). "ErbB2 has been shown to play an important role in the pathogenesis of certain aggressive types of breast cancer." (PMID 23326595, 2013). "In the current report, we sought to determine the antitumor activity of MM-121 in combination with paclitaxel against erbB2-overexpressing breast cancer using both in vitro and in vivo models." (PMID 24168763, 2013). "In human breast cancer cell lines with amplified ERBB2 expression, depletion of ERBB3 reduces cell proliferation to the same extent as depletion of ERBB2, while loss of ERBB1 (epidermal growth factor receptor (EGFR)) does not affect proliferation." (PMID 23593223, 2013). "MM-121 significantly enhances trastuzumab-induced growth inhibition in erbB2+ breast cancer cell lines." (PMID 24215614, 2013). "In support of this point, the expression of PGC-1α and that of the glutamine pathway are positively correlated in ERBB2+ breast cancer patients, and high expression of glutamine metabolism enzymes is associated with shorter survival." (PMID 24304688, 2013). "This genetic cross was performed to ensure that deletion of LKB1 occurred in every mammary tumor cell transformed by ErbB2 in vivo." (PMID 24280377, 2013). "Gab2 is overexpressed in estrogen receptor-positive cells, and a subset of breast cancers is driven by Gab2 overexpression coupled with RTK ErbB2 (also known as Neu or HER2) receptor signaling." (PMID 23431498, 2013). "In breast cancer, ErbB2 has proven to be an excellent target; however, only 25% of cancer patients are eligible for an ErbB2-directed therapy." (PMID 23343422, 2013). "We demonstrate that loss of LKB1 promotes tumor initiation and induces a characteristic shift to aerobic glycolysis (‘Warburg effect’) in a model of ErbB2-mediated breast cancer." (PMID 24280377, 2013). "Since 1994, several studies have shown the presence of immune response against Her2 in patients with ERBB2+ breast cancer." (PMID 23614022, 2013).
breast cancer (continued). "Several studies have reinforced the significance of c-MYC as an ERBB2 effector and the functional role that the two genes play in breast cancer progression." (PMID 23421821, 2013). "Here, we demonstrate the prognostic value of the ERBB2 gene in cat mammary tumours, identifying this gene into a potential therapeutic target, similar to the results demonstrated for HBC." (PMID 24386251, 2013). "The laboratory of Dr. Brad Nelson has engineered the first immunological mouse model for ErbB2-driven breast cancer." (PMID 23408142, 2013). "The expression of glutamine enzymes (glutamine cluster) was positively correlated with PPARGC1A expression in the basal and ERBB2-enriched breast cancer subtypes, in agreement with the fact that these subtypes have the highest expression of PPARGC1A." (PMID 24304688, 2013). "Although a -500 bp promoter has been shown to be active in all breast cancer cell lines tested, a promoter fragment between -6007 and -3798 actively enhances transcription in ErbB2-overexpressing cells." (PMID 23242156, 2013). "To date, no study has been initiated to test the activity of MM-121 in breast cancer patients with erbB2-overexpressing tumors, including those resistant to paclitaxel." (PMID 24168763, 2013). "Lapatinib, an oral reversible tyrosine kinase inhibitor that blocks both ErbB1 and ErbB2, crossed the blood-brain barrier, and combined with capecitabine resulted in partial and complete responses of BM from HER-2 positive breast cancers." (PMID 23348930, 2013). "In this context, we report that the c-MYC gene repressor MBP-1 negatively regulates ERBB2 gene transcription in SKBr3 breast cancer cells by targeting regulatory sequences in the promoter region." (PMID 23421821, 2013). "We have also utilized ErbB2-expressing breast cancer cells in which LKB1 levels have been reduced using shRNA approaches." (PMID 24280377, 2013). "In the mouse, Cited1 is up-regulated in MMTV-Cre/FloxNeoNeuNT mammary tumours and associates with the transcription factor EGR2 to regulate the expression of the oncogene ErbB2 (HER2, Neu)." (PMID 23935526, 2013). "In this study, we provide novel observations regarding the transcriptional control of the ERBB2 gene in SKBr3 breast cancer cells." (PMID 23421821, 2013). "To demonstrate the biological significance of the changes in glutamine gene expression, we first quantified relative glutamine uptake in ERBB2/Neu-induced breast cancer cells with increased expression of PGC-1α (α-1.1) and control cells." (PMID 24304688, 2013). "Multiple mouse models overexpressing ERBB2 in mammary glands have been established, all of which lead to development of mammary tumors." (PMID 23593223, 2013). "Along the same line, a Phase I study of neratinib and temsirolimus, an mTOR inhibitor, demonstrated encouraging antitumor activity in patients with ERBB2-overexpressing NSCLCs and breast cancers." (PMID 23630663, 2013). "In this context, the present study performed on human BT474 and SKBR3 breast cancer cells opens a new perspective in order to enhance the sensitivity of ErbB2-directed treatments and to avoid escape mechanisms." (PMID 23308242, 2013). "Reduced LKB1 expression is associated with diminished cell-to-cell contact and enhances the migratory and invasive properties of established ErbB2-driven breast cancer cells." (PMID 24280377, 2013). "In contrast, phase II clinical trials in cervical cancer and ErbB2-positive breast cancer patients detected toxicity when the two drugs were combined." (PMID 23937707, 2013). "Although cat mammary neoplasias are considered to be a natural model of human breast cancer, molecular information on benign and malignant lesions, particularly regarding the cat ERBB2 gene and erbB-2 protein, is still scarce." (PMID 24386251, 2013). "MM-121 has been demonstrated to exert antitumor activity in preclinical models of human cancers, including erbB2+ breast cancer." (PMID 24215614, 2013).
breast cancer (continued). "Our study provides significant insight into the complex autocrine and paracrinefunctions of mammary epithelial COX-2 in ErbB2-induced breast cancer and suggests thattumor cell COX-2 is an important component in establishing a permissive immunemicroenvironment." (PMID 24004819, 2013). "Since ERBB2 is frequently amplified or overexpressed in breast cancer, we used its 3′UTR as a driver for EPOR levels through miR-125b decoy." (PMID 24165569, 2013). "We chose Erbb2 and Wnt1 as the initiating oncogenes, because their gene products activate two distinct pathways that are frequently altered in human breast cancer." (PMID 24381245, 2013). "The combination of MM-121 and trastuzumab not only inhibits erbB2-overexpressing breast cancer cell proliferation, but also promotes the otherwise trastuzumab-resistant cells undergoing apoptosis in an in vivo xenografts model." (PMID 24215614, 2013). "Our data showed that treatment of certain erbB2+ breast cancer cell lines with MM-121 resulted in a dramatic inhibition on PI-3K/Akt signaling, the major determinant of trastuzumab resistance in breast cancer." (PMID 24215614, 2013). "In the future, it will be interesting to test the impact of blocking Ret in other sub-types of breast cancer, particularly in ErbB2/HER2 positive and basal-like models." (PMID 23868506, 2013). "Here, we study the antitumor activity of an anti-erbB3 antibody MM-121/SAR256212 in combination with paclitaxel against erbB2-overexpressing breast cancer." (PMID 24168763, 2013). "In the present study, we provide evidence that MBP-1 inhibits the expression of the ERBB2 gene in SKBr3 breast cancer cells by interacting with the promoter region." (PMID 23421821, 2013). "In 20-30% of breast cancers, ERBB2, a member of the ERBB family of receptors, is overexpressed resulting in a malfunction of control points in the cell division process and unrestricted growth." (PMID 23829771, 2013). "As the other member of the family, ERBB2, a known proto-oncogene located on the long arm of human chromosome 17 (17q12), is overexpressed in cancers such as breast cancer, with approximately 30% amplification or over-expression of the gene." (PMID 24223781, 2013). "This fact also sustains the recent suggestion that quantification of ERBB2 mRNA transcripts by RT-qPCR can be used to determine prognoses in breast cancer as an additional molecular test to the erbB-2 IHC test." (PMID 24386251, 2013). "Perturbation of protein tyrosine kinase signaling results in malignant transformation, as seen in ErbB2/HER2/Neu overexpression in breast cancer and the NPM-ALK fusion gene in anaplastic large cell lymphoma." (PMID 24349301, 2013). "We previously reported that ectopic expression of EBP1 decreases ErbB2 protein levels in human breast cancer cell lines." (PMID 23242156, 2013). "Both PGC-1α and ERRα have been shown to promote the growth of ERBB2+ tumors in vivo and to regulate the metabolism of this specific breast cancer subtype." (PMID 24304688, 2013). "We demonstrate that targeting of erbB3 with the blocking Ab MM-121 significantly enhances paclitaxel antitumor activity against erbB2-overexpressing breast cancer cells in our in vitro and in vivo models." (PMID 24168763, 2013). "We independently identified an immune signature, comprising B and T cell-specific genes, which is elevated in mouse mammary tumors that are impaired in ErbB2 signaling relative to wild-type tumors." (PMID 23408142, 2013). "ERBB2 amplification in breast cancers is targeted with Trastuzumab and Lapatinib but these are only some recent examples." (PMID 23863689, 2013). "JBCRG-08 was a randomized, multicenter, open-label, phase III study of adjuvant lapatinib, trastuzumab, their sequence, and their combination in patients with HER2/ErbB2-positive primary breast cancer (BIG 2-06/N063D/EGF 106708)." (PMID 23494592, 2013).
breast cancer (continued). "Cluster 2 (dark-blue) consisted of genes that are up-regulated in HER2+ breast cancer, including ERBB2, GRB7, STARD3 and PSMD3 that are located in the HER2 amplicon." (PMID 23945349, 2013). "Herein, we investigate the antitumor activity of MM-121/SAR256212, a fully human anti-erbB3 antibody (Ab), against two erbB2-overexpressing breast cancer cell lines resistant to trastuzumab." (PMID 24215614, 2013). "The expressions of steroid hormone receptors such as estrogen receptor (ER) and progesterone receptor (PR), and the oncogene ErbB-2/human epidermal growth factor receptor 2 (HER-2) are important factors in distinguishing breast cancer subtypes." (PMID 23476649, 2013). "The network analysis indicated alterations in a number of cancer related pathways, including p38 MAPK, PI3K/AKT, ERK/MAPK and NF-κB signaling pathways, and a potential role of TGFA, ErbB2, and IL-1/IL-1R in young women with breast cancer." (PMID 23704896, 2013). "Our data supports further exploration of the combinatorial regimens consisting of MM-121 and paclitaxel in breast cancer patients with erbB2-overexpressing tumors, particularly those resistant to paclitaxel." (PMID 24168763, 2013). "The majority of RTKs that are expressed in breast cancer cells, including ErbB2 and Met, couple to ShcA." (PMID 23408142, 2013). "To investigate the functional role of LKB1 in breast cancer development and progression, we developed an LKB1-deficient mouse model of ErbB2-induced mammary tumorigenesis." (PMID 24280377, 2013). "ZNF703 was recently identified as a novel breast cancer oncogene in the 15% of breast cancers that harbor 8p12 amplifications, amplified second only to the well-known oncogenes, ERBB2 and cyclin D1 (CCND1)." (PMID 23991038, 2013). "Recently, PTPN12 was found to interact with and dephosphorylate the RTKs EGFR and ErbB-2, thereby acting as a tumor suppressor in breast cancer by suppressing MAPK signaling." (PMID 23785422, 2013). "In breast cancer, the ErbB2 specific antibody trastuzumab is now routinely given in combination with chemotherapy to ErbB2/HER2-positive breast cancer patients and has had a significant impact on patient mortality." (PMID 23868506, 2013). "Taken together our results show a mechanism for EPO/EPOR and ERBB2 co-regulation in breast cancer and confirm the importance of miR-125b in controlling clinically-relevant cancer features." (PMID 24165569, 2013). "Overall, this network is a modification of that proposed by Birtwistle in order to account the characteristics of preclinical breast cancer model based on BALB/c mice transgenic for the transforming rat ErbB2 oncogene, BALB-neuT mice." (PMID 23734974, 2013). "Our data support further studies to explore the therapeutic potential of MM-121 in combination with trastuzumab in breast cancer patients whose tumors overexpress erbB2 and become resistant to trastuzumab." (PMID 24215614, 2013). "Our data suggest that MM-121 is efficacious in all erbB2-overexpressing breast cancer cell lines tested." (PMID 24168763, 2013). "Co-expression of erbB3 and erbB2 is frequently observed in breast cancers and breast cancer cell lines, and erbB3 plays an important role in breast cancer development driven by erbB2 amplification/overexpression." (PMID 24215614, 2013). "It has been well-documented that activation of the erbB3 signaling plays a pivotal role in the development of erbB2-overexpressing breast cancer." (PMID 24168763, 2013). "Altogether, these studies indicate the involvement of several factors regulating ERBB2 gene transcription in breast cancer cells." (PMID 23421821, 2013). "With this approach, we intended to contribute new data regarding the role of the ERBB2 gene in the cat mammary tumour system." (PMID 24386251, 2013). "In human breast cancer, it is one of the most down-regulated miRNAs and is able to modulate ERBB2/3 expression." (PMID 24165569, 2013).
breast cancer (continued). "In keeping with this, other studies have shown that nuclear ErbB-2 is involved in the progression of breast carcinoma." (PMID 23638030, 2013). "We should emphasise that our IHC and RT-qPCR results assigned the analysed cat mammary primary malignant lesions to a subtype of cat mammary carcinomas that are characterised by ERBB2 RNA and erbB-2 protein underexpression." (PMID 24386251, 2013). "Small molecule TKIs and neutralizing monoclonal antibodies that target the EGF receptor (EGFR) and/or the closely related ERBB2 (HER2/neu) have had success in treatment of non-small cell lung carcinoma and breast carcinoma." (PMID 24260357, 2013). "To evaluate the role of FAK in ErbB2 mammary tumour progression, we interbred mice carrying conditional FAK alleles to separate transgenic strains carrying either MMTV-Cre or MMTV-activated ErbB2 (NDL 2-5)." (PMID 22373082, 2012). "Remarkably, five distinct ERBB2-positive breast cancer concepts (two from cell lines and three from tumor cohorts) were independently associated with this LD PR-gene signature." (PMID 22697792, 2012). "The human epidermal growth factor receptor 2 (referred to as HER-2 or ErbB2) is a membrane tyrosine kinase overexpressed in 25-30% of human breast cancers." (PMID 23148787, 2012). "This research group originally planned to image the binding of radiolabeled anti-ErbB2 (Herceptin) to breast cancers but unexpectedly found that anti-ErbB2 also bound to the hearts of some patients." (PMID 22912742, 2012). "Up to date, cyclooxygenase-2 (COX-2) gene is the only one whose expression has been shown to be modulated through the role of ErbB-2 as a TF in mammary tumor cells." (PMID 22356700, 2012). "While dominant pro-oncogenic functions like those described for the ErbB2 kinase in breast cancer occur frequently in solid tumors, alterations in phosphatases likewise occur and function as tumor suppressors." (PMID 22279592, 2012). "Her-2 (ErbB-2), Estrogen Receptor (ER) and Progesterone Receptor (PR) are the most commonly used biomarkers and therapeutic targets in breast cancer patients." (PMID 22957061, 2012). "For example, RAR-L3 (8p21.2) and RAR-L5 (17p12), where PPP2R2A and MAP2K4 are located, respectively, and RAR-G13 (17q12), where ERBB2 is located, were consistently detected in a recent large-scale breast cancer genetic subgroup study." (PMID 22938721, 2012). "Anti-HER2 antibodies were tested using five breast cancer cell lines with different ERBB2 copy numbers." (PMID 23033967, 2012). "Our data further suggest that breast cancers with elevated ErbB2 expression and compromised PTPN13 expression and/or function would benefit the most from this type of dual targeting." (PMID 22279592, 2012). "In the ErbB2 over-expressed breast cancers therapy the anti-HER2 monoclonal antibody, trastuzumab (Herceptin) can be used." (PMID 23133437, 2012). "The advancement of targeted therapies such as trastuzumab, a humanized anti-ErbB2 antibody, improves survival of Her2 breast cancer patients." (PMID 22279592, 2012). "This is exemplified by the choice of the oncogene ERBB2/HER2 as drug target in ERBB2/HER2-positive breast cancer." (PMID 22363779, 2012). "In HER-2-overexpressed breast cancer, ErbB2 activates NF-κB via signaling that includes PI3K, PDK1, Akt, protein kinase 2 (CK2), and CKBBP1." (PMID 21876713, 2012). "The mice used for examining the effect of ErbB2-induced mammary tumors was obtained by breeding Lcn2−/− (C57BL/6) mice with MMTV-ErbB2 (FVB/N) mice." (PMID 22737251, 2012). "Data from Phase 2 trials have recently confirmed this impressive anti-tumour activity of 17-AAG and validated HSP90 as a therapeutic target for ERBB2/HER2-driven breast cancer." (PMID 22621282, 2012). "With respect to ERBB2, the most frequently used method to determine its expression in breast cancer is immunohistochemistry (protein quantification)." (PMID 22253826, 2012).